HRH4 (histamine receptor H4)
Description:
G protein-coupled receptor primarily expressed in immune cells such as mast cells, eosinophils, basophils, dendritic cells and neutrophils that plays a key role in immune and inflammatory responses. Mediates chemotaxis of immune cells to sites of inflammation or injury by responding to histamine. Activation by histamine also influences the release of proinflammatory cytokines such as TNF, CCL4, IL6 and IFN-gamma. Ligand binding induces a conformation change that triggers signaling via G(i)/GNAI1 leading to decreased intracellular cAMP levels by inhibiting adenylate cyclase activity. In addition, plays a role in the control of renal reabsorption processes, particularly albumin uptake (By similarity).
Synonyms: H4R; HH4R; GPCR105; AXOR35; GPRv53; BG26; H4
Tractability: Small molecule: a drug acting on it is in phase 2 or 3 trials; a structure with a bound ligand is known; a high-quality ligand is known; it belongs to a druggable protein family. Antibody: UniProt places it where antibodies can reach, with high confidence; its Gene Ontology location is reachable by antibodies, with high confidence; UniProt predicts a signal peptide or a membrane-spanning region. PROTAC: a small molecule that binds it is known.
Target class: Family A G protein-coupled receptor; Small molecule receptor (family A GPCR); Histamine receptor; Membrane receptor; Monoamine receptor
Chemical probes: JNJ-39758979 (high quality)
Gene: Protein-coding gene on chromosome 18 (24,460,637 to 24,479,961, forward strand). Ensembl gene ENSG00000134489.
Subcellular location: Cell membrane
Pathways (Reactome):
Signal Transduction: G alpha (i) signalling events; Histamine receptors
Gene Ontology:
Molecular function: protein binding; histamine receptor activity; neurotransmitter receptor activity; G protein-coupled receptor activity
Biological process: adenylate cyclase-inhibiting G protein-coupled receptor signaling pathway; adenylate cyclase-inhibiting G protein-coupled acetylcholine receptor signaling pathway; chemical synaptic transmission; G protein-coupled receptor signaling pathway, coupled to cyclic nucleotide second messenger; G protein-coupled receptor signaling pathway; inflammatory response; positive regulation of cytosolic calcium ion concentration; regulation of MAPK cascade
Cellular component: plasma membrane; dendrite; synapse; membrane
Genetic constraint (gnomAD): Loss-of-function variants: 10 observed, 9.14 expected, observed/expected ratio (o/e) 1.09, 90% interval 0.67 to 1.76. That is too few expected variants to judge how well the gene tolerates losing a copy. Missense variants: 384 observed, 435.81 expected, observed/expected ratio (o/e) 0.88, 90% interval 0.81 to 0.96. Synonymous variants: 140 observed, 159.35 expected, observed/expected ratio (o/e) 0.88, 90% interval 0.76 to 1.01.
Homologues: Orthologues: chimpanzee HRH4 (99% identical), macaque HRH4 (94% identical), dog HRH4 (72% identical), pig HRH4 (72% identical), rat Hrh4 (69% identical), mouse Hrh4 (68% identical), rabbit HRH4 (68% identical), guinea pig HRH4 (65% identical). Paralogues in human: HRH3 (40% identical), CHRM3 (24% identical), CHRM2 (22% identical), HRH1 (22% identical), CHRM5 (22% identical), CHRM1 (21% identical), DRD1 (21% identical), DRD3 (21% identical), CHRM4 (20% identical), HTR4 (20% identical), TAAR9 (20% identical), DRD5 (20% identical), and 13 more.
Diseases named in the same sentence as HRH4 in open-access papers:
HRH4 is named in the same sentence as 101 diseases in open-access papers, as found by Europe PMC text mining. Sharing a sentence is not in itself a finding about the gene and the disease. The quoted sentences say what the papers report.
asthma (23 papers, 2010 to 2025). "Indeed, a few studies have reported that HRH4 polymorphisms are involved in multiple disorders, such as allergic rhinitis, ankylosing spondylitis, atopic dermatitis, asthma." (PMID 31133025, 2019). "This is why there are clinical tests being conducted with the aim of verifying the usefulness and safety of using selective HRH4 antagonists in allergic and autoimmune diseases, including asthma, rheumatoid arthritis, and atopic dermatitis." (PMID 34829764, 2021). "Asthma and AR share eight common genes (CLC, EMR4P, IL5RA, FRRS1, HRH4, SLC29A1, SIGLEC8, IL1RL1) that are presumed to describe the link for multimorbidity." (PMID 36825519, 2023).
Pruritus (17 papers, 2015 to 2025). Pruritus is an itch or a sensation that makes a person want to scratch. "Previous studies have indicated that IL-31, IL-4Rα, JAK1, and HRH4 are strongly associated with pruritus in AD." (PMID 34970141, 2021). "Additionally, interleukin (IL)-31 is closely associated with AD-induced pruritus, which synergistically works with histamine H4 receptor (HRH4) to aggravate pruritus and skin lesions." (PMID 34925005, 2021). "To further investigate the anti-pruritus mechanisms underlying HLJDT, we analyzed pruritus-related markers (i.e., JAK1, HRH4, IL-4αR, GRP, SP, and TRPV-1) from the dorsal root ganglion." (PMID 34925005, 2021).
breast carcinoma (16 papers, 2009 to 2026). "In our previous investigation, we have found that variants of HRH4 gene were significantly associated with the risk and malignant degree of breast cancer in Chinese Han populations." (PMID 24835231, 2014). "Therefore, with respect to the notion that genetic factors contribute greatly to the risk and development of breast cancer, polymorphisms of HDC, HNMT, HRH3 and HRH4 are likely to be also associated with breast cancer risk." (PMID 24835231, 2014). "The interactions are visually represented in a diagram, showing that HRH1, HRH2, and HRH4 are central to the network, indicating their significant roles in breast cancer pathology." (PMID 39267843, 2024). "On the other hand, the main role in breast cancer and melanoma was attributed to HRH4, which in the presented results, had the lowest expression in all stages." (PMID 36902343, 2023). "The role of HRH4 in breast cancer cell proliferation and expression of GNA15, and different chemokines in small intestinal neuroendocrine neoplasia, pancreatic ductal adenocarcinoma, and ovarian cancer was also observed." (PMID 36902343, 2023). "Recently, accumulated evidence indicates that histamine receptor H4 (HRH4) also plays a role in cell proliferation, both in normal and malignant cells, including hematopoietic progenitor cells, breast cancer cells and pancreatic carcinoma cells." (PMID 21609450, 2011).
atopic dermatitis (15 papers, 2014 to 2025). "Interestingly, polymorphisms in the HRH4 gene were found to be associated with atopic dermatitis, while variants of the IL1RL1 gene have been associated with atopic dermatitis and atopic asthma." (PMID 27421833, 2016).
colon cancer (6 papers, 2009 to 2023). "Another study stated that HRH4 expression in CRC tissue and normal colon mucosa was present, and HRH1, HRH2, and HRH4 in human colon cancer cells: HT29, Caco-2, and HCT116." (PMID 36902343, 2023). "In the current study, we showed that HRH4 activation could promote the 5-Fu-mediated cell apoptosis in colon cancer cells, which may provide new clues for histamine receptor-targeted therapies of CRCs." (PMID 21609450, 2011).
colorectal cancer (4 papers, 2009 to 2023). A primary or metastatic malignant neoplasm that affects the colon or rectum. "Previously, we reported the decreased expression of HRH4 in colorectal cancers and revealed its correlation with tumor proliferation." (PMID 22363581, 2012). "Recent evidence suggests that the expression level of histamine receptor H4 (HRH4) is abnormal in colorectal cancer tissues." (PMID 21609450, 2011). "In vitro studies using colorectal cell line showed that alteration of HRH4 expression on colorectal cancer cells affected histamine-mediated cell growth control, implicating the cAMP/PKA pathway in this progress." (PMID 21609450, 2011). "We first assessed the expression of HRH4 in 12 colorectal cancer cell lines." (PMID 21609450, 2011). "HRH4 stimulation resulted in cell growth arrest and increase of cyclin-dependent kinase inhibitor p21Cip1 and p27 Kip1, cell cycle regulators with important functions in cell cycle control and apoptosis of colorectal cancer cells." (PMID 21609450, 2011). "These details may help us answer the question of whether direct or indirect effects of histamine, or both, mediated by HRH4, are responsible for tumor progression in colorectal carcinoma." (PMID 21609450, 2011). "In colorectal cancers, expression levels of HRH4 mRNA were reduced regardless of the grade or Dukes classification of the tumors." (PMID 22363581, 2012).
gastric cancer (3 papers, 2012 to 2021). A primary or metastatic malignant neoplasm involving the stomach. "Down-regulation of HRH4 in gastric carcinomas plays a role in histamine-mediated growth control of gastric cancer cells." (PMID 34367971, 2021). "Some studies show that deletion of HRH4 gene is present in gastric cancer cases and is closely correlated with attenuated gene expression." (PMID 34367971, 2021). "Down-regulation of HRH4 in gastric carcinomas plays a role in histamine-mediated growth control of GC cells." (PMID 22363581, 2012). "In the current study, we aimed to investigate the abnormalities of HRH4 gene in gastric carcinomas (GCs)." (PMID 22363581, 2012). "In addition, immunohistochemical images from HPA indicated high levels of IL-17RA protein and low levels of HRH4 protein in gastric cancer tissues." (PMID 34367971, 2021). "In addition, immunohistochemical images from HPA indicated low levels of HRH4 protein and high levels of IL-17RA protein in gastric cancer tissues." (PMID 34367971, 2021). "We first assessed the expression of HRH4 in several gastric cancer cell lines." (PMID 22363581, 2012). "Until now, however, little is known whether there are any abnormalities of HRH4 gene in gastric carcinomas (GCs)." (PMID 22363581, 2012).
inflammatory bowel disease (3 papers, 2015 to 2023). A spectrum of small and large bowel inflammatory diseases of unknown etiology. "Interestingly, although HRH subtypes differ in their associated functions and their distribution throughout the human body, HRH4 is expressed in the GI tract and altered expression levels have been linked to inflammatory responses that are related to inflammatory bowel diseases and cancer." (PMID 31378678, 2019).
Sepsis (3 papers, 2011 to 2022). Sepsis is defined as life-threatening organ dysfunction caused by a dysregulated host response to infection. "The potential ability to suppress CYP1A1 or inhibit intestinal cadaverine-HRH4 signaling to enhance IEC junctions, or a combination of these two strategies, warrants further study to develop more effective sepsis treatment." (PMID 35572636, 2022). "HRH4 has been reported to influence apoptosis in animal models of sepsis through counteracting the anti-apoptotic action of NF-kappaB, while the cAMP-PKA pathway is involved in HRH4 activation-mediated cell death in peripheral blood mononuclear cells (PBMCs)." (PMID 21609450, 2011).
autoimmune conditions (2 papers, 2019 to 2022). "For example, copy-number variations of the human histamine H4 receptor (HRH4) gene have been shown to be associated with AD, as well as a number of other autoimmune conditions such as SLE." (PMID 30798353, 2019).
colorectal tumors (2 papers, 2009 to 2011). "The aim of this study is to evaluate the clinical and molecular phenotypes of colorectal tumors with abnormal HRH4 expression." (PMID 21609450, 2011). "Moreover, only limited data on the level of HRH4 expression in colorectal tumors have been reported." (PMID 21609450, 2011). "Nonetheless, whether HRH4 plays a role in the epithelium of alimental canal or colorectal tumor progression remains unclear." (PMID 21609450, 2011).
atherosclerosis (1 paper, 2024). A disease characterized by the build-up of fatty material and calcium deposition in the arterial wall resulting in partial or complete occlusion of the arterial lumen. "Among major findings, our results suggest a role of triglyceride-associated and mast-cell functional genes FCER1A, MS4A2, GATA2, HDC, and HRH4 in atherosclerosis risks." (PMID 39276247, 2024).
cognitive deficits (1 paper, 2026). "Given the promising effects of microglial Hrh4 deletion in early stages of AD, it is critical to further evaluate its potential to reverse cognitive impairments in the advanced stage of AD, which are highly relevance to AD patients." (PMID 41134085, 2026). "To explore the cell type‐specific effects of Hrh4‐deletion in AD progression, we evaluated the beneficial effects of neuronal and microglial Hrh4‐deletion in ameliorating cognitive deficits and pathogenesis." (PMID 41134085, 2026). "Notably, However, deletion of Hrh4 in microglia significantly rescued this cognitive deficit, increasing the recognition index to baseline levels seen in controls." (PMID 41134085, 2026). "Mechanistically, deletion of Hrh4 in microglia, but not in neurons, reverses cognitive deficits and mitigates key AD pathogenesis by activating the cAMP/TGF‐β1/Smad3 pathway." (PMID 41134085, 2026).
COVID-19 (1 paper, 2023). A disease caused by infection with severe acute respiratory syndrome coronavirus 2. "Testes of COVID-19 patients also presented elevated mRNA levels of histamine H4 receptor (HRH4), cyclooxygenase-2 (COX2) and monocyte chemoattractant protein-1 (MCP1; 10x higher)." (PMID 36797789, 2023).
endometriosis (1 paper, 2025). The growth of functional endometrial tissue in anatomic sites outside the uterine body. "Using gene expression data from the database provided by the University of Turku, we analyzed the expression levels of histamine receptors HRH1, HRH2, HRH3, and HRH4 across various endometriosis subtypes and control tissues." (PMID 41516088, 2025). "Specifically, HRH2 and HRH4 were detected in nerve fibers of peritoneal endometriosis, whereas HRH1–HRH3 were expressed in nerve fibers of deep infiltrating endometriosis." (PMID 41516088, 2025).
Hypertension (1 paper, 2025). The presence of chronic increased pressure in the systemic arterial system. "In this study, we employed histidine decarboxylase (HDC)‐Cre transgenic rats, Hrh4‐knockout (KO) mice, and two hypertensive models (SHRs and stress‐induced hypertensive rats) to investigate H4R as a potential central target for hypertension management." (PMID 41017599, 2025).
Mediterranean fever (1 paper, 2015). "The G protein-coupled receptor (Hrh4), as well as, Mediterranean fever (Mefv), the inducible heme oxygenase-1(Hmox1) and the Neutrophil cytosol factor 1 (Ncf1) were hubs in the network associated with inflammatory responses." (PMID 25902940, 2015).
viral infection (1 paper, 2024). "Interestingly, the HRH4antagonist JNJ-7777120 inhibited viral infection at drug concentrations greaterthan 25 μM, suggesting that HRH4 might weakly mediate viral infection." (PMID 38953634, 2024).
tumor (24 papers, 2009 to 2026). "These included genes known to be expressed by microglia (CCL8, SPP1, IRF7, IL1RAP), macrophages (IL1RN, SPP1, PDPN, IL1RAP, MDK, TFRC, HRH4), and tumor-associated macrophages (IL6, SPP1)." (PMID 22937035, 2012). "At the protein level, we observed significantly higher concentrations of HRH1, HRH2, and HRH4 in tumor tissues than those in control tissues (p < 0.05)." (PMID 39267843, 2024). "In another interesting report, inhibition of the Hrh4 expression in CRC resulted in inhibition of tumor growth and tumor progression." (PMID 26907350, 2016). "Overall, our results first revealed the presence of the abnormalities of HRH4 in GCs and suggested its potential role in histamine-mediated regulation of tumor growth." (PMID 22363581, 2012). "Eight of these immune response genes (SPP1, PDPN, IL1RN, IL6, CCL8, MDK, IRF7, and HRH4) were expressed between 1.25–1.59 fold higher in the microglia/macrophage enriched population compared to bulk tumor." (PMID 22937035, 2012). "IL-2-activated NK cells express the histamine receptor H4 which induces NK cell chemotaxis, that might be towards the tumor site if specific anti-tumor antibodies are present." (PMID 31167464, 2019).
cancer (23 papers, 2009 to 2025). A tumor composed of atypical neoplastic, often pleomorphic cells that invade other tissues. "It was stated that blocking HRH4 by its antagonists may inhibit cancer cell proliferation and its deficiency also reduced CRC development in experimental mice." (PMID 36902343, 2023). "Slight discrepancies were observed for CALM2 in G1 cancer and for HRH4 in G3 cancer." (PMID 34768392, 2021). "Next, our results showed that the expression of HRH1-HRH4, especially HRH1, HRH3 and HRH4, was dramatically upregulated in AIDS-KS tissues from two cancer patients when compared to those in normal skin tissues." (PMID 37112991, 2023). "High expression of EDN1, HRH2, and HRH4 promoted worse OS in non-luminal HER2+ cancers." (PMID 39267843, 2024).
adenocarcinoma (1 paper, 2016). A common cancer characterized by the presence of malignant glandular cells. "Adenocarcinoma cells immunohistochemically expressed Hrh1, Hrh2, Hrh3 and Hrh4 with varied intensities." (PMID 26907350, 2016).
gastrointestinal tumor (1 paper, 2011). "While the role of H1R and H2R in different gastrointestinal tumor models is well documented, the relevance of HRH4 has yet to be clarified." (PMID 21609450, 2011).
HRH4 also shares sentences with these, for which no sentence is quoted: allergic disease (13 papers); dermatitis (11); colitis (10); Arthritis (7); melanoma (7); allergic rhinitis (5); Allergy (5); rheumatoid arthritis (5); allergic asthma (4); experimental autoimmune encephalomyelitis (4); Alzheimer disease (3); cholangiocarcinoma (3); diabetic nephropathy (3); lung carcinoma (3); triple-negative breast carcinoma (3); autoimmune disease (2); eczema (2); immune diseases (2); inflammation (2); lung fibrosis (2); pancreatic carcinoma (2); Parkinson’s (2); psoriasis (2); urticaria (2); vestibular disorder (2); adenoma (1); age-related macular degeneration (1); agranulocytosis (1); allergic conjunctivitis (1); allergic contact dermatitis (1).
A further 49 diseases each share a sentence with HRH4 in 1 paper.